GPR143 (G protein-coupled receptor 143)
Description:
Receptor for tyrosine, L-DOPA and dopamine. After binding to L-DOPA, stimulates Ca(2+) influx into the cytoplasm, increases secretion of the neurotrophic factor SERPINF1 and relocalizes beta arrestin at the plasma membrane; this ligand-dependent signaling occurs through a G(q)-mediated pathway in melanocytic cells. Its activity is mediated by G proteins which activate the phosphoinositide signaling pathway. Also plays a role as an intracellular G protein-coupled receptor involved in melanosome biogenesis, organization and transport.
Synonyms: OA1; NYS6
Tractability: Antibody: UniProt places it where antibodies can reach, with high confidence; its Gene Ontology location is reachable by antibodies, with high confidence; UniProt predicts a signal peptide or a membrane-spanning region.
Target class: Membrane receptor
Gene: Protein-coding gene on chromosome X (9,724,039 to 9,786,297, reverse strand). Ensembl gene ENSG00000101850.
Subcellular location: Melanosome membrane; Lysosome membrane; Apical cell membrane
Subcellular location (Human Protein Atlas): Plasma membrane; Golgi apparatus; Nuclear bodies; Nucleoplasm
Pathways (Reactome):
Signal Transduction: Amine ligand-binding receptors; G alpha (q) signalling events
Developmental Biology: Regulation of MITF-M-dependent genes involved in pigmentation
Gene Ontology:
Molecular function: dopamine binding; G protein-coupled receptor activity; L-DOPA binding; L-DOPA receptor activity; L-tyrosine binding; protein binding
Biological process: G protein-coupled receptor signaling pathway; melanosome localization; melanosome organization; melanosome transport; phospholipase C-activating G protein-coupled receptor signaling pathway; eye pigment biosynthetic process; signal transduction; visual perception; neuropeptide signaling pathway; regulation of melanosome organization; regulation of melanosome transport
Cellular component: apical plasma membrane; Golgi apparatus; lysosomal membrane; melanosome; melanosome membrane; plasma membrane; cytoplasm; membrane
Gene-disease validity (ClinGen):
ClinGen rates the evidence that GPR143 causes each of these diseases.
GPR143-related foveal hypoplasia (X-linked): Definitive. Any foveal hypoplasia with or without albinism caused by a variant in the GPR143 gene.
Homologues: Orthologues: chimpanzee GPR143 (99% identical), macaque GPR143 (97% identical), guinea pig GPR143 (80% identical), mouse Gpr143 (78% identical), rat Gpr143 (77% identical), dog GPR143 (69% identical), tropical clawed frog gpr143 (63% identical), zebrafish gpr143 (54% identical).
Diseases named in the same sentence as GPR143 in open-access papers:
GPR143 is named in the same sentence as 51 diseases in open-access papers, as found by Europe PMC text mining. Sharing a sentence is not in itself a finding about the gene and the disease. The quoted sentences say what the papers report.
ocular albinism (32 papers, 2006 to 2025). Albinism affecting the eye in which pigment of the hair and skin is normal or only slightly diluted. "GPR143 is a seven‐transmembrane G‐coupled receptor that causes ocular albinism when mutated in mammals (Bueschbell, Manga, and Schiedel 2022)." (PMID 39910963, 2025). "Due to concern for possible ocular albinism, he underwent genetic testing in 2009 at the age of 6 months-old by a commercial laboratory for a variant in GPR143." (PMID 40869959, 2025). "In a patient with ocular albinism, a hemizygous c.703G>A:p.(Glu235Lys) variant in GPR143 was initially filtered due to the low sequence depth of the region (8 reads)." (PMID 38819824, 2024). "Individuals with GPR143-associated ocular albinism had significantly increased odds for shorter (≤22 mm) eyes." (PMID 35704304, 2022). "Significant odds for a short AL were seen for GPR143-associated ocular albinism (adjusted OR, 56.20; P < 0.001), TYR-associated albinism (adjusted OR, 34.19; P < 0.001), and RPE65-associated disease (adjusted OR, 12.52; P < 0.01)." (PMID 35704304, 2022). "Average ALs in TYR- and OCA2-associated albinism and in GPR143-associated ocular albinism are similar to those of the reference cohorts in younger patients." (PMID 35704304, 2022). "WGS identified a pathogenic hemizygous mutation in GPR143: c.11C>G, p.(Pro4Arg) confirming the diagnosis of ocular albinism (OA1)." (PMID 33808351, 2021). "In summary, we used data obtained by WES to identify a novel deep intronic mutation c.659-131 T > G in GPR143 in a Japanese family with male siblings affected by ocular albinism and congenital nystagmus." (PMID 26061757, 2015). "Here, we focus on the role of the G-protein-coupled receptor OA1 (also known as GPR143), which is expressed exclusively in pigmented cells and mutations in which cause the most common type of ocular albinism." (PMID 24006264, 2013). "GPR143 resides at Xp22 and mutations within it are primarily linked to ocular albinism (OA), where nystagmus results as a secondary phenotype." (PMID 21904664, 2012). "This is the first report that p.Y269X mutation of GPR143 gene is responsible for the pathogenesis of familial ocular albinism." (PMID 22916221, 2012). "It is unclear how the mutated GPR143 causes the ocular abnormalities, such as macular hypoplasia in people with ocular albinism." (PMID 22916221, 2012). "Most of GPR143 mutations were reported in a large collection of patients mainly with ocular albinism." (PMID 22916221, 2012). "Nystagmus has been reported in ocular albinism patients with mutations of GPR143 and is thought to be a secondary phenotype in these patients." (PMID 21423867, 2011). "Nystagmus has been reported in ocular albinism patients with mutations in GPR143 and is thought to be a secondary phenotype in these patients." (PMID 18523664, 2008). "GPR143 mutations can cause ocular albinism, a disease characterized by severe retinal hypopigmentation, foveal hypoplasia, reduction of visual acuity, and optic misrouting." (PMID 18523664, 2008). "Previous studies have included an extensive survey of GPR143 mutations in a large collection of patients with ocular albinism." (PMID 18523664, 2008). "Of 19 diseases, 10 had >10 participants: ABCA4 retinopathy; CNGB3- and CNGA3-associated achromatopsia; RPGR-associated disease; RPE65-associated disease; blue cone monochromacy (BCM); Bornholm eye disease (BED); TYR- and OCA2-associated oculocutaneous albinism; and GPR143-associated ocular albinism." (PMID 35704304, 2022). "In a Korean family with a GPR143 c.623C>A, p.(Ala208Glu) variant, one affected male displayed typical ocular albinism signs with severe hypopigmentation with clearly visible choroid vessels in the entire retina and eye movement recording showed a horizontal, conjugate pendular nystagmus." (PMID 33498813, 2021). "However, one of the classical OA phenotypes, ocular albinism, has rarely been observed in patients with GPR143 mutations." (PMID 21423867, 2011).
ocular albinism (continued). "Another gene, GPR143, also known as the OA1 gene at Xp22, causes ocular albinism upon mutation." (PMID 18523664, 2008). "Therefore, we speculated that the GPR143 c.659-131 T > G mutation affects the splicing of the GPR143 primary transcript and may cause ocular albinism." (PMID 26061757, 2015). "However, a recent study of a Chinese family with X-linked CN, occurring without the classical phenotype (retinal hypopigmentation) of ocular albinism but only with nystagmus (some patients also suffer from foveal hypoplasia and reduction of visual acuity), has identified a GPR143 gene mutation." (PMID 18523664, 2008). "G protein-coupled receptor 143 (GPR143) is encoded by the ocular albinism 1 (OA1) gene, which was first cloned because of its role in the pathogenesis of ocular albinism, a disorder caused by dysfunction of pigment producing cells." (PMID 35495622, 2022). "By comparison, in the GPR143 group, one patient (20%) had exotropia, and two patients (40%) had ocular albinism (OA)." (PMID 33732697, 2021). "G-protein coupled receptor 143 (GPR143), also known as OA1, was primarily described to cause ocular albinism with nystagmus as a prominent concomitant symptom." (PMID 33732697, 2021). "Protein products from OA1 (GPR143; GPCR, G-protein-coupled receptor), i.e., the ocular albinism type 1 gene, encode pigment cell-specific GPCR confined to melanosomes within the cell, which is also a target gene for MITF." (PMID 34360837, 2021). "In summary, the sponge GPCR repertoire contains four of the five GPCR GRAFS families, as well as other GPCR gene families including cAMP-like receptors, intimal thickness-related receptor like (ITR-like), lung 7TM and GPR143 (ocular albinism) receptors." (PMID 25528161, 2014). "Ocular albinism is caused by mutations in the ocular albinism I (OA1; or G protein-coupled receptor 143 [GPR143]) gene (OMIM 300500)." (PMID 20806075, 2010). "Three of five mutations (c.703G>A, c.733C>T, c.250+1G>C) in GPR143 were detected in three cases without ocular albinism in our study." (PMID 33732697, 2021). "Moreover, we identified a putative homolog of GPR143 (PF02101), which in humans and other mammals is associated with ocular albinism." (PMID 25528161, 2014). "With respect to GPR143, this argument suggests that GPR143 signaling controls RPE paracrine release of something critical for retinal development and survival, because of the noted sensory retinal developmental defects when GPR143 is mutated, as in ocular albinism." (PMID 32276449, 2020). "However, in our study, none of the patients with the GPR143 mutation had the classical phenotype of ocular albinism." (PMID 19390656, 2009). "However, in our family of subjects, none of the patients with the GPR143 mutation had the classical phenotype of ocular albinism." (PMID 18523664, 2008). "Noted, there is a form of albinism, ocular albinism (OA1), affecting the eyes, but does not affect the hair and skin, which is caused by the mutation in G protein-coupled receptor 143 gene (GPR143; OMIM 300808)." (PMID 28629449, 2017). "However, GPR143 mutations have also been found to cause a variant form of OA with IIN as the most prominent and only consistent finding and has been reported in IIN families, without the classical phenotype of ocular albinism." (PMID 21904664, 2012). "Since the discovery of L-DOPA as potential ligand for GPR143, many studies have been conducted based on this finding, for example clinical studies to evaluate L-DOPA as a therapy for ocular albinism, which were not conclusive." (PMID 35495622, 2022). "Without a functional GPR143 protein, melanosomes in the RPE and melanocytes of the skin become abnormally large, but it is unclear how these macromelanosomes are related to vision abnormalities in patients with ocular albinism." (PMID 24098784, 2013).
ocular albinism type 1 (32 papers, 2005 to 2025). "Ocular albinism type 1 (OA1) is an X-linked disorder caused by mutations in the GPR143 gene, leading to ocular features such as nystagmus, foveal hypoplasia, and reduced visual acuity." (PMID 41426868, 2025). "Hemizygous mutations in GPR143 on chromosome Xp22, commonly cause ocular albinism type I (OMIM 300500); however, in a smaller number of cases, it has been reported to cause isolated congenital nystagmus-6 (OMIM 300814)." (PMID 33498813, 2021). "Pathogenic variants of G-protein coupled receptor 143 (GPR143) gene often leads to ocular albinism type I (OA1) characterized by nystagmus, iris and fundus hypopigmentation, and foveal hypoplasia." (PMID 33785018, 2021). "Among the three cases with X-linked ocular albinism, two cases had a deletion of GPR143, and one case was unclear." (PMID 32670353, 2020). "Six genes are associated with autosomal recessive OCA (TYR, OCA2, TYRP1, SLC45A2, SLC24A5 and LRMDA), and one gene, GPR143, is associated with X-linked ocular albinism (OA)." (PMID 30679655, 2019). "One participant had GPR143-associated X-linked ocular albinism and another proband had biallelic variants in SLC38A8, a glutamine transporter gene associated with foveal hypoplasia and optic nerve misrouting without pigmentation defects." (PMID 31719542, 2019). "Since GPR143 is the only candidate gene for non-syndromic X-linked ocular albinism, we used Sanger sequencing to confirm the underlying gene mutation." (PMID 28211458, 2017). "In GPR143-associated X-linked ocular albinism, the major peak was also at shorter lengths." (PMID 35704304, 2022). "Moreover, in NIR-AF images acquired from carriers of X-linked ocular albinism (GPR143/OA1), the fundus presents as a mosaicism in which patches of NIR-AF signal correspond to pigmented areas and alternate with patches of darkness." (PMID 31015497, 2019). "GPR143 (G protein-coupled receptor 143) at Xp22 is primarily linked to ocular albinism type 1." (PMID 26268155, 2015). "The mutations in GPR143 have been reported to cause ocular albinism type 1 (OA1)." (PMID 22262942, 2012). "A few individuals initially misdiagnosed with congenital nystagmus have been shown to be affected by ocular albinism type 1 by screening GPR143." (PMID 19390656, 2009).
albinism (30 papers, 2005 to 2026). A congenital disorder characterized by partial or complete absence of melanin pigment in the eyes, hair, or skin. "A multicentre study of 907 patients with FH found that 67% of individuals had albinism caused by variants in GPR143, OCA2, TYR and HPS1 genes, followed by 21.8% with PAX6, 6.8% with SLC38A8 and 3.5% with FRMD7 variants." (PMID 37762234, 2023). "TYR- and GPR143-associated albinism was identified as having a higher risk of shorter ALs compared to the reference population." (PMID 35704304, 2022). "However, mutations in GPR143, one of the genes associated with albinism, result in the impairment of visual pathway, but with intact melanin synthesis machinery." (PMID 33732697, 2021). "Mutations in GPR143 may cause isolated albinism in the eye or a series of other abnormalities, such as reduced visual acuity, nystagmus, and strabismus." (PMID 33732697, 2021). "Since 1986, we have proposed that DOPA may itself also function as a neurotransmitter Several lines of evidence suggest that G protein‐coupled receptor 143 (GPR143), originally identified as the gene product of ocular albinism 1 (OA1), an X‐linked type of albinism, acts as a receptor for DOPA." (PMID 41510670, 2026). "Many of these loci encompass variants previously linked to retinal layer thickness parameters (including TSPAN10 and LINC00461) while a subset of them has been linked to monogenic disorders, most notably, albinism (including TYR, OCA2 and GPR143)." (PMID 40666342, 2025). "Molecular genetic diagnosis for most patients started with a next-generation sequencing (NGS) panel targeting genes associated with albinism—TYR, OCA2, MC1R, MITF, SLC45A2, TYRP1, and GPR143—as the initial clinical diagnosis for all patients was albinism." (PMID 39457042, 2024). "Other diagnoses detected among Africans include albinism (GPR143 and TYR genes), Senior–Loken Syndrome (NPHP4 gene), and X-linked retinoschisis (RS1 gene)." (PMID 36836473, 2023). "Another of the EoHM-related genes is GPR143 (OMIM:300808), which is expressed in the retinal pigment epithelium and is associated with the development of albinism and nystagmus." (PMID 35457050, 2022). "Researchers proposed that GPR143 signaling was the downstream of pigmentation, and all forms of albinism were dependent upon GPR143 signaling pathway to affect retinal development." (PMID 33732697, 2021). "Can the visual deficits reported in people with albinism be rescued by stimulating a known participant of the pigmentation pathway, GPR143?" (PMID 32276449, 2020). "Each of the various mutations in different genes that cause albinism either lead to a reduction of tyrosinase activity and associated loss of L-DOPA production or loss of the receptor for L-DOPA, GPR143." (PMID 32276449, 2020). "First of all, this study demonstrates that the sequencing of whole genes, as we did here with our current diagnostic panel that contains the entirety of five major albinism genes (TYR, OCA2, SLC45A2, GPR143 and HPS1), is instrumental in identifying deep intronic splice variants in these genes." (PMID 39201349, 2024). "Although no typical albinism symptoms were observed, GPR143 mutation screening should be required for patients with poor visual function." (PMID 33732697, 2021). "In addition, GPR143 sits at the most interesting place in the pigmentation pathway, where it separates RPE pigmentation from the hallmark albinism-associated retinal defects." (PMID 32276449, 2020). "Twenty-nine (30%) patients had albinism caused by variants in TYR gene, 23 (24%) had OCA2, 14 (15%) had x-linked albinism with variants in GPR143 gene, 13 (13%) had other genetically verified types of albinism and in the remaining 17 (18%) the genetic cause of albinism could not be established." (PMID 38136112, 2023).
albinism (continued). "The genes identified for MAC were KMT2D, MAB2IL2, ALDH1A3; ASDA were KERA, PAX6, MYOC, TGFBI, and SLC4A11; congenital cataract were CRYBB2, EPHA2, HSF4 and BCOR; infantile nystagmus were CACNA1A and FRMD7; and albinism were OCA2, GPR143, HPS6 and SLC38A8." (PMID 32830442, 2020). "We screened 172 patients with clinical signs of albinism for sequence variations in genes most prevalent in human OCA and OA (TYR, OCA2, and GPR143)." (PMID 21541274, 2011). "We present a molecular analysis of TYR, P, TYRP1, MATP and GPR143, well known candidate genes for OCA and OA1 types, in 23 (OCA-22 and OA-1) South Indian families (36 affected individuals with a positive history of albinism)." (PMID 20806075, 2010). "In the present study, we analyzed 122 heterozygous patients with albinism either by whole genome sequencing or by the use of our next-generation sequencing panel that includes the entire sequence of the TYR, OCA2, SLC45A2, GPR143 and HPS1 genes (exons, introns, flanking sequences)." (PMID 39201349, 2024). "It has been found from some studies that, unlike the TYR gene-related albinism, GPR143 gene-related albinism is more likely to be complicated with a short ocular axis." (PMID 37749571, 2023). "The most common cause of foveal hypoplasia is albinism, but no mutations were identified in SLC45A2, TYR, TYRP1, GPR143, OCA1, OCA2, OCA3, or OCA4." (PMID 28546991, 2017). "Genetic analysis revealed seven coding variants in the cohort that were presumed to be albinism-causing and, to the authors’ knowledge, have not previously been reported: three in TYR, one in OCA2, one in TYRP1, one in SLC45A2, and one in GPR143." (PMID 38441889, 2024). "Although no differential expression of GPR143 was observed as in mammals’ albinism, the identification of other G-protein coupled receptor including GPR21 and GPR61 may imply their possible involvement in fish albinism." (PMID 28777813, 2017).